BRCA1 (BRCA1 DNA repair associated)
Diseases named in the same sentence as BRCA1 in open-access papers (continued):
Sharing a sentence is not in itself a finding about the gene and the disease.
colorectal cancer (continued). "Herein, we sought to evaluate the ability of colorectal cancer-derived EVs to transform the BRCA1-KO fibroblasts into colon cancer cells." (PMID 31200749, 2019). "Here, ERCC1 and BRCA1, which are linked to lymph node metastasis (LNM) in colorectal cancer (CRC), were evaluated in primary CRC samples from Chinese patients with LNM (LNM CRC) or without LNM (non-LNM CRC)." (PMID 23496813, 2013). "The aim of this study was to investigate whether the TME, specifically HA and its metabolism members, could influence the expression of tumor supressor genes BRCA1 and 2, thereby contributing to tumorigenic processes in breast and colorectal cancer." (PMID 41373491, 2025). "Colorectal cancer (CRC) with HR deficiency (HRD), developed via biallelic somatic variants of HR-related genes, including BRCA1/2, were more frequent in MSI-H/dMMR than in MMS/pMMR, suggesting a significant association between alterations in the HRD pathway and dMMR." (PMID 38615286, 2024). "KCTD5 has been identified as having a role in cell migration 28, 29; and GET4, as part of a larger protein complex with BAG6, has been shown to play a role in the recruitment of BRCA1 to sites of DNA damage 30 and promote tumour growth in models of colorectal cancer." (PMID 37771787, 2023). "In this meta-analysis, we were surprised to find a potential protective effect of BRCA gene mutations against colorectal cancer in three studies that did not distinguish between BRCA1 and BRCA2." (PMID 37644384, 2023). "This study aimed to investigate whether BRCA1 and BRCA2 gene mutations are associated with colorectal cancer risk." (PMID 37644384, 2023). "The link between BRCA1 and homologous recombination deficiency (HRD) in cancer has gained importance with the emergence of new targeted cancer treatments, while the available data on the role of the gene in colorectal cancer (CRC) remain contradictory." (PMID 35280729, 2022). "Germline pathogenic variants in BRCA1 gene have not been causally linked to an increased risk of familial colorectal cancer, but the reports on the subject are contradictory." (PMID 35280729, 2022). "Among our most important findings is a possible relationship between high BRCA1 expression and young age of colorectal cancer diagnosis, providing a starting point to investigate the puzzling rise in colorectal cancer incidence and mortality among young people for which little explanation exists." (PMID 34611475, 2021). "Breast cancer type 1 susceptibility protein (BRCA1)‐associated protein (BAP1) is a marker of poor prognosis in several cancers, including uveal melanoma, renal cell carcinoma, cholangiocarcinoma, non‐small cell lung cancer, and colorectal cancer." (PMID 33529461, 2021). "Recent studies show that BRCA1-deficient fibroblasts treated with uveal melanoma-derived and colorectal cancer-derived EVs transfer malignant traits to target cells, and the authors suggest that BRCA1 activity is necessary to prevent the detrimental effects of cancer-derived EVs in non-cancer cells." (PMID 34283059, 2021). "Further studies are required to elucidate the real-world value of TMB analysis in MC colorectal cancer with or without BRCA1/2 mutation." (PMID 32377194, 2020). "Overall, BARD1-BRCA1 involvement in MMR is underexplored, but this connection could explain the incidence of colorectal cancer (CRC) in BRCA1- and BARD1-mutated CRC patients as MMR defects have long been known to predispose individuals to CRC." (PMID 32708251, 2020).
colorectal cancer (continued). "In addition, at the end of the treatment period, an aliquot of BRCA1-KO fibroblasts exposed to EVs isolated from the serum of a female colorectal cancer patient was karyotyped." (PMID 31200749, 2019). "Other studies supported the prognostic significance of BRCA1 in colorectal cancer." (PMID 30479693, 2018). "While whether colorectal cancer should be included into screening of BRCA1/2 associated HBOC was not identified." (PMID 36463302, 2022). "Out of three recent meta-analyses, one of them found an increased risk of colorectal cancer associated with BRCA1 variants (odds ratio = 1.49, 95% CI = 1.19 to 1.85, P < 0.001), while the other two did not identify any increase in CRC risk among patients carrying a BRCA1 variant." (PMID 35280729, 2022). "Furthermore, low BRCA1 protein expression may be a biomarker for worse prognosis in colorectal cancer." (PMID 34611475, 2021). "Colorectal cancer risk increases in BRCA1 but not in BRCA2 mutation." (PMID 32349445, 2020). "Similarly, there was no excess of colorectal cancer, although BRCA1 mutations appear to confer an elevated risk for colon cancer." (PMID 11875732, 2002). "Initially, known hereditary cancer syndromes and their associated pathogenic variants were thought to be related to a single tumor type, such as BRCA1/2 in BC and APC or the DNA mismatch repair genes in colorectal cancer." (PMID 40564925, 2025). "However, whether BRCA2 mutations increase the risk of colorectal cancer remains controversial; some studies suggest that BRCA1 pathogenic variants may be associated with colorectal cancer risk, while BRCA2 variants are not." (PMID 39985003, 2025). "A limitation of both the FFPE BRCA1/2 panel testing and the FFPE inherited colorectal cancer panel testing is that at present, the amplicon-based technology cannot detect large genomic rearrangements (>40 base pairs in size)." (PMID 33654310, 2021). "In the present study, we exposed BRCA1-KO fibroblasts to extracellular vesicles (EVs) isolated from a colon cancer cell line (HT29) and from sera of patients with colorectal cancer." (PMID 31200749, 2019). "Indeed, truncated BRCA1 has been shown to antagonize wild-type BRCA1 function in a dominant-negative manner, and several lines of evidence support the view that truncated APC contributes to colorectal cancer by causing spindle misalignment that eventually leads to chromosomal instability." (PMID 25107276, 2014). "BRCA1 and 2 protein expressions were evaluated in TT and NAT in breast and colorectal cancer." (PMID 41373491, 2025). "The cancer risks in female relatives of BRCA1 carriers and non-carriers were not significantly different with respect to gastric, pancreatic, and colorectal cancers." (PMID 36861435, 2023). "Differences in the risks for other cancers (liver, gastric, and colorectal cancers) between female relatives of BRCA1 and BRCA2 carriers were not significant." (PMID 36861435, 2023). "Different NGS studies have reported that up to 18% of patients under 50 years old, diagnosed with colorectal cancer, have a PV in genes that are not traditionally associated with this neoplasm such as ATM, CHEK2, and BRCA1/2." (PMID 36232851, 2022). "Colorectal cancer is not included in the BRCA1/2 tumor spectrum; published guidelines do not recommend increased detection of this type of neoplasm in carriers of mutations in these genes." (PMID 36232851, 2022). "In particular, recent published works point out at other genes implied in colorectal cancer pathogenesis (APC, MUTYH, STK11 and BRCA1/2) as explanations of familial colorectal cancer syndromes in patients who do not present mutations in standard MMR protein gene system." (PMID 26485756, 2015).
colorectal cancer (continued). "The strength of the family history of colorectal cancer would not, however, be in keeping with the slight increases in colorectal risk seen with BRCA mutations; these are usually seen in those with BRCA1 mutations rather than BRCA2." (PMID 19493351, 2009). "The combinations of MINAS in BRCA1/2 and BRCA/Lynch made up the majority of the cases identified and likely reflect ascertainment and testing bias, as these genes are commonly screened for simultaneously in response to the cancers that are prevalent worldwide like breast and colorectal cancers." (PMID 39843919, 2025). "However, a recent meta-analysis concluded that BRCA1 and/or BRCA2 mutation carriers are not at a higher risk of colorectal cancer." (PMID 37296477, 2023). "However, Co-IP experiment showed that PIPKIγ did not interact with BRCA1 directly in colorectal cancer cells." (PMID 35673560, 2022). "Second, it is possible that we missed pathogenic germline variants in moderate penetrance colorectal cancer genes such as ATM, SMAD3, or high penetrance syndromes primarily associated with other cancers such as BRCA1 and BRCA2, which were not part of our panel." (PMID 31647837, 2019). "Interestingly, in colorectal cancer models, the CEP72 protein interacts with BRCA1 during mitosis, and its overexpression decreases BRCA1 expression and induces chromosomal instability, which could also explain its putative relevance in EOC." (PMID 30149579, 2018). "In contrast to the FFPE BRCA1/2 testing cohort, the impact of a negative panel result on the clinical management of relatives in the FFPE inherited colorectal cancer testing cohort was minimal." (PMID 33654310, 2021).
hereditary cancer (140 papers, 2003 to 2025). Malignant neoplasms occurring in families at a rate greater than that expected by chance and caused by germline mutations in a specific gene. "Carcinogenesis depends on the interactions between BRCA1 and BIP; therefore, BIP mutations should be observed in BRCA1 familial cancers." (PMID 40136510, 2025). "To date, extensive research on the risk of hereditary cancer and prevalence of BRCA1/2 PVs in women was performed, whereas little is known about this in men harboring germline BRCA1/2 alterations." (PMID 38974244, 2024). "For the investigation, we used rare missense variants of 28 genes associated with hereditary cancers, including BRCA1/2." (PMID 37380723, 2023). "Determination of the status of mutations in the BRCA1/2 genes is important for the identification of a predisposition to familial cancer and for the selection of proper therapy." (PMID 35300046, 2022). "The D13S317-region harboring 13q22-31 exhibited higher LOH (69%) in BRCA1-associated adnexal carcinomas, thus harboring putative tumor suppressor genes involved in the carcinogenesis of this hereditary cancer." (PMID 35456396, 2022). "Though the benefit of BRCA1/2 tumor testing is increasingly evident for the purposes of therapeutic decision‐making, the importance of identifying non‐BRCA1/2‐associated hereditary cancer families cannot be overlooked." (PMID 33030818, 2021). "Genetic alterations of HR factors including BRCA1/2 cause hereditary cancer such as hereditary breast and ovarian cancer syndrome." (PMID 36860287, 2021). "Our ability to identify the risk variants in the BRCA1 and BRCA2 (BRCA1/2) proteins is a valuable source of information about hereditary cancer patients." (PMID 34207612, 2021). "We examined the KConFab cohort, which is enriched for familial cancer mutations, for co-occurrence of germline BRCA1 mutation and high cyclin E1 expression." (PMID 34465787, 2021). "As a result of the increased availability to genetic testing for hereditary cancers, and improved models for functional assessment, the proportion of unclassified variants in BRCA1/BRCA2 has been progressively decreasing over time." (PMID 30400234, 2018). "The prevalence of hereditary cancers attributed to pathogenic variants in the BRCA1 and BRCA2 genes in unselected BC patients from Latin America and the Caribbean varies from 1.2% in Columbia to 27.1% in the Bahamas." (PMID 30400234, 2018). "In the recent past, testing of panels of susceptibility genes for hereditary cancer has replaced BRCA1/2 testing." (PMID 30400234, 2018). "In this study, we aim at describing the mutation spectrum and frequencies in the BRCA1/2 carrier population of the largest clinic of hereditary cancer in Norway." (PMID 29339979, 2018). "Wider application of multigene panel tests that include high-penetrance cancer susceptibility genes, so-called “beyond BRCA1/2 genes”, will likely provide clinically relevant information for some patients with high risk for hereditary cancer." (PMID 29338689, 2018). "POFT cancers have shared genetic backgrounds as parts of hereditary cancers related to BRCA1 and BRCA2 mutations and Lynch syndrome." (PMID 30089478, 2018). "POFT cancers are well established hereditary cancers based on mutations in BRCA1, BRCA2, and mismatch repair genes." (PMID 30089478, 2018). "It is important to not only offer the AJ population screening for the three known BRCA1/2 AJ founder mutations, but also other pathogenic mutations associated with hereditary cancer within this population." (PMID 30152102, 2018). "Correlations between reduced BRCA1 expression and some aggressive tumor features in our study were, to some extent, similar to those described in previous studies of familial cancers with BRCA1 germline mutation." (PMID 28863181, 2017). "Hereditary cancers associated with germ-line mutations in BRCA1/2 have recently been found to display specific patterns of genomic alterations that likely result from defective HR DNA repair." (PMID 29021619, 2017).
hereditary cancer (continued). "Identification of founder mutations of BRCA1/2 in high risk communities can have a significant impact on the management of hereditary cancer at the level of the national healthcare systems, making genetic testing more affordable and cost-effective." (PMID 29138730, 2016). "Before the advent of NGS, patients who underwent germ-line genetic testing for hereditary cancer were typically tested for a limited number of genes that were strongly associated with a single hereditary cancer syndrome, such as BRCA1/2 or the Lynch genes." (PMID 26681312, 2016). "Within the identified alterations in BRCAX tumors, several regions have been previously identified in similar studies for non-BRCA1/2 familial cancer, such as loss in 11q and 16q, and gains in 1q and 8q." (PMID 26979459, 2016). "In conclusion, despite the low frequency of the deleterious mutations in non-BRCA1/2 predisposing genes, multigene panel genetic testing is an alternative tool for screening familial cancer patients in the clinic." (PMID 26436112, 2015). "Hereditary cancer panels have been constructed incorporating genes underlying well characterized cancer syndromes, such as BRCA1 and BRCA2, along with more recently discovered genes associated with increased cancer risk." (PMID 25886519, 2015). "Understanding tissue specific differences in DNA repair pathways can shed light on the tissue specificity of familial cancer-predisposing mutations in genes such as BRCA1, BRCA2, or APC." (PMID 25033455, 2014). "A deleterious BRCA1 mutation was found in 43/106 (40.6%) of familial cancer cases and in 27/592 (4.6%) of sporadic cases." (PMID 23536787, 2013). "Clinically, the focus of PARP-1 is as a target for the treatment of familial cancers, such as BRCA1/2 deficient breast and ovarian tumors." (PMID 24202328, 2013). "Among studied patients, at least one from nine different BRCA1 mutations was shown in over 11% of sporadic cases and 21% of familial cancers, which is in agreement with previous findings for women in Poland." (PMID 24171766, 2013). "The distribution of the BRCA1 mutations by ethnicity was as follows: 8 Latvian (29.6% of hereditary cancer families from the same ethnic group), 1 (6%) Russian, 3 (100%) Polish, 2 (100%) Ukrainian and 1 (50%) Belarusian." (PMID 23767878, 2013). "The DNA mismatch repair genes breast cancer susceptibility gene 1 (BRCA1), human MutL homologue 1 (hMLH1) and human MutS homologue 2 (hMSH2) have also been linked to a predisposition for familial cancer." (PMID 22735547, 2012). "In this study, we found that BRCA1-associated cancers have a different histological profile and can be distinguished from other familial cancers." (PMID 15642173, 2005). "Account is taken of both these facts in the Scottish NHS guidelines for management of familial cancers, hence favouring ascertainment of BRCA1 mutation-bearing families." (PMID 12698193, 2003). "PARPI therapy (alone or in combination with ARSI) is the preferred first-line targeted option for patients with pathogenic HRR alterations detected in either tissue or ctDNA, with genetic counseling indicated for germline BRCA1/2 carriers due to the associated hereditary cancer risk." (PMID 41440220, 2025). "Nevertheless, additional education or post-test genetic counselling may be of benefit to ensure that cancer patients understand their results, particularly when testing genes like BRCA1/2 where many PV are germline in orgin and confer a hereditary cancer risk." (PMID 35418215, 2022).